STAT1 (signal transducer and activator of transcription 1)
Diseases named in the same sentence as STAT1 in open-access papers (continued):
Sharing a sentence is not in itself a finding about the gene and the disease.
psoriasis (continued). "Th17 cells exert an effect by secreting IL-17A, IL-17F, IL-26, and TNF in psoriasis, forming a feedforward inflammatory network with KCs, activating STAT-1 and NF-κB signaling pathway, and inducing keratinocytes (KCs) to secrete several pro-inflammatory factors." (PMID 32377228, 2020). "Although the molecular mechanisms involved in the pathogenesis of psoriasis are complex, growing evidence suggests that the activator of transcriptions 1 and 3 (STAT1 and STAT3), and nuclear factor-κB (NF-κB) is pivotal in the transcriptome network involved in the mechanism of psoriasis." (PMID 30894513, 2019). "Moreover, miR-17-92 cluster is increased in psoriasis and can be elevated by cytokines in keratinocytes via STAT1 signaling pathway." (PMID 29752469, 2018). "Previous studies have shown both an increased expression of STAT1 in psoriatic skin and an increased STAT1 activity as measured by elevated phosphorylation levels of STAT1(Tyr701) and STAT1(Ser727), which suggests that STAT1 plays a role in the pathogenesis of psoriasis." (PMID 28472186, 2017). "In addition, STAT1-57 genes were repressed in psoriasis lesions following treatment of patients with biologic agents, including anti-TNF therapy (P = 2.1×10−8; GSEA), anti-IL-17A therapy (P = 9.9×10−8; GSEA) and efalizumab (P = 4.5×10−12; GSEA)." (PMID 24260178, 2013). "The list of the DEG in common in the 4 studies contains many genes known to be upregulated in psoriasis, such as IFNγ-regulated genes STAT-1, STAT-3 and MX1; antimicrobial peptides (beta defensin 4, lipocalin 2, S100A7); and pro-inflammatory proteins such as IL-8, CXCL1, IL-1F9, TNFSF10/TRAIL." (PMID 20422035, 2010). "Moreover, IDL was more effective than EL at repressing expression of inflammatory genes, including genes involved with T-cell activation, unhealthy skin signature genes and co-expressed IFN response genes within the STAT1-57 module that becomes activated in psoriasis and some skin cancers." (PMID 41465291, 2025). "UVB repressed Oct1, an IFN-γ-independent transcription factor for HLA-C that modulates HLA-C expression and, similar to STAT1 and IRF1, is a transcriptional regulator of differentially expressed genes in psoriasis lesions." (PMID 40243413, 2025). "In psoriasis, KRT17 expression is specifically induced through IFN-γ through the STAT1 signaling pathway." (PMID 41479908, 2025). "Collectively, this study demonstrates a role for ALOX15B in the resolution of psoriasis through modulation of EGFR and STAT1 via lipid peroxidation." (PMID 39843435, 2025). "Total glucosides of paeony repressed the phosphorylation of STAT1 and STAT3, thus attenuating animal psoriasis." (PMID 39167035, 2024). "In immune cells activated by chronic inflammation, the transcription of STAT1 and STAT3 promotes cytokine secretion during psoriasis." (PMID 36838711, 2023). "IFN-γ is involved in the pathogenesis of psoriasis by activating JAK1 and STAT1 transcription factors in skin lesions." (PMID 36838711, 2023). "STAT1 and STAT3 have recently emerged as key players in the development and pathogenesis of psoriasis." (PMID 36838711, 2023). "We constructed the predicted PPI networks and functional modules related to psoriasis and atopic dermatitis and distinguished the key candidate target genes CXCL8, STAT1, and MMP9 in the diagnosis and therapy of similar pathogenesis." (PMID 35586812, 2022). "STAT1 and NF-κB activation were also confirmed in the IMQ-induced psoriasis model to define the biological activity of CD." (PMID 34641629, 2021). "Cytokines such as IFN-γ, IL-17A or IL-22 bind to cell surface receptors and the signal transduction occurs through JAKs, which in turn promotes STAT1 and/or STAT3 phosphorylation and activation in psoriasis." (PMID 33986690, 2021). "Overexpression of CHUK, IKBKB, NFKBIA, NFKB1, JAK2, STAT1 and STAT3, as inflammation related factors, was detected in the psoriasis model group." (PMID 34834106, 2021).
psoriasis (continued). "To further validate the correlation of STAT1 and S100A7 with SPRR2C in psoriasis, we next evaluated the STAT1 and S100A7 protein levels and distribution in the psoriatic lesional and normal control tissue samples." (PMID 33452236, 2021). "We also identified 36 KDs that were shared across multiple psoriasis supersets and tissue-specific regulatory networks, such as LCK and STAT1." (PMID 30642337, 2019). "In this study, MEDD reduced the numbers of inflammatory cells and IL-17 by decreasing STAT1 and STAT3 in IMQ-induced psoriasis." (PMID 31791315, 2019). "Notably, genes such as Nlrp3, Casp1, Casp4, IL-1β, IL-18, and Stat1 had high degree values, indicative of their significant position in the PPI network and potential targets for FZHFZY treatment of psoriasis." (PMID 41383588, 2025). "In addition, ChIP-seq experiments have identified multiple transcription factor peaks, including AP2-, AP2-, STAT1, STAT3, as well as FOXA1, which has binding sites overlapping with two loci (2q13 for acne and 2q11.2 for psoriasis)." (PMID 39975900, 2025). "STAT1 conducts type I interferon and type II interferon signaling, which allows Interferon-γ (IFN-γ) to sensitize keratinocytes and allow inflammatory cells to enter the psoriasis lesion stage." (PMID 40560938, 2025). "Meanwhile, STAT1 and STAT3 have been shown to be involved in the cytokine–cytokine receptor interaction pathway, and indeed, these targets are involved in suppressing the pathology of immune-mediated inflammation in psoriasis." (PMID 37631075, 2023). "TSG-6 produced by MSCs-IT can reduce neutrophil infiltration in psoriasis mouse model by decreasing the expression of CXCL1, which may be related to the reduced level of STAT1 phosphorylation." (PMID 36433947, 2022). "In addition, CXCL8, STAT1, and MMP9 were upregulated in both psoriasis and atopic dermatitis disease model samples vs. normal samples by the Western blot analyses." (PMID 35586812, 2022). "We brought forth the conclusion that CXCL8, STAT1, and MMP9 may essentially implicate in disease of psoriasis and atopic dermatitis as the potential therapeutic targets." (PMID 35586812, 2022). "Specifically, two STAT molecules, STAT1 and STAT3, are crucial in the pathogenesis of psoriasis." (PMID 34884596, 2021). "Furthermore, overexpression was detected for the JAK2, STAT1 and STAT3 genes, which is in agreement with previous reports utilizing similar combinatorial stimulation used for modeling psoriasis in keratinocytes." (PMID 33986690, 2021). "Taken together, our experimental analysis showed that dysregulation of the ceRNA circuit comprised of PRKCQ‐AS1, has‐miR‐545‐5p and STAT1 act as a vital regulatory role in JAK/STAT signalling pathway activation, which involve in the hyper‐inflammation of keratinocytes in psoriasis." (PMID 34080300, 2021). "A proposed MOA for DMF treatment of MS and psoriasis therefore builds on GSH depletion increasing hemoxygenase-1 expression, impairing STAT1 (signal transducer and activator of transcription 1) phosphorylation, and hereby inhibiting Th1 and Th17 (T helper cell 1 and 17) differentiation." (PMID 30341347, 2018). "Within psoriasis lesions, IFN-γ may play a dominant role, since induction of STAT1-57 genes was strongest in KCs following treatment with IFN-γ, with strong, but slightly weaker, induction following treatment with IFN-α." (PMID 24260178, 2013). "We identified a motif resembling the interferon-stimulated response element (ISRE) enriched in genome regions near STAT1-57 genes (i.e., G(A/G)AANNGAAA(C/G)T), and most of the STAT1-57 genes strongly increased in psoriasis lesions featured this motif near the TSS." (PMID 24260178, 2013). "Moreover, the expression of p-STAT1 and p-STAT3 was elevated in the dermis of PS+T, analogous with the results of the T cell secretory profile and contributing to the activation loop of psoriasis." (PMID 37597582, 2023).
psoriasis (continued). "In this study, the oral administration of CD alleviated the characteristics of psoriasis in the IMQ-induced mice model and CD decreased the activation of keratinocytes via the inhibition of pro-inflammatory cytokine production by suppressing the activity of STAT1 and the NF-κB pathways." (PMID 34641629, 2021). "All other DEGPs could be placed along a continuum, with some showing greater psoriasis specificity (e.g., DBI, GLTP, HRNR, KRT73, ELOVL7), and others showing similar expression shifts in many or most skin diseases (e.g., MX1, S100A8, S100A9, STAT1, LAP3)." (PMID 26251673, 2015). "Our experimental results revealed that JAK2, STAT1 and PI3K were activated, while AKT was not influenced at a protein level in the psoriasis-like model." (PMID 34834106, 2021). "Upregulation of the STAT1/NOS2 pathway has not been reported in HI before; however, it has been described in other inflammatory skin diseases, such as psoriasis and atopic dermatitis, sharing characteristics of skin barrier impairment and increased inflammation." (PMID 32544098, 2020).
atherosclerosis (52 papers, 2009 to 2025). A disease characterized by the build-up of fatty material and calcium deposition in the arterial wall resulting in partial or complete occlusion of the arterial lumen. "Collectively, we provide detailed insights into MØ-specific IFNγ-activated transcriptional changes, mediated by STAT1-PU.1 co-binding and associated epigenetic changes, and offer the identification of new biomarkers and therapeutic targets in atherosclerosis." (PMID 40607379, 2025). "Accordingly, we provide detailed insights into MØ-specific IFNγ-activated transcriptional changes, mediated by STAT1-PU.1 co-binding and associated epigenetic changes, and offer the identification of new biomarkers and therapeutic targets in atherosclerosis." (PMID 40607379, 2025). "STAT1 has been identified as a possible therapeutic target for atherosclerosis, and PKM and PTGIS have been identified as risk markers of atherosclerosis." (PMID 39796045, 2024). "In the cardiovascular context, STAT1 activation has been associated with ischemic disease progression, and IFNs are known to contribute to plaque progression in atherosclerosis." (PMID 34638942, 2021). "Future studies should therefore seek to understand the effect of both ERK1 and ERK2 deficiency on atherosclerosis development and STAT1 S727‐mediated changes in cellular processes." (PMID 34569651, 2021). "On this basis, we would have expected similar effects of ERK1 deficiency and STAT1 S727 phosphorylation on atherosclerosis development in vivo." (PMID 34569651, 2021). "Atherosclerosis RT2 Profiler PCR Array analysis showed that ERK1 deficiency and STAT1 S727A modification produced significant changes in the macrophage expression of 18 and 49 atherosclerosis‐associated genes, respectively." (PMID 34569651, 2021). "STAT1 has been identified as a regulator of foam cell formation and atherosclerotic lesion development in an intraperitoneal inflamemation model and an atherosclerosis-susceptible bone marrow transplantation mouse model." (PMID 31588227, 2019). "ERK is also integral to the IFN-γ-mediated activation of STAT1 and the expression of key genes implicated in atherosclerosis." (PMID 26006249, 2015). "For example, inhibition of IFNγ-induced STAT1 signaling protects against atherosclerosis development and IFNγ is associated with the development of AT in obese patients and diminishes insulin signaling in human adipocytes." (PMID 22403661, 2012). "In murine atherosclerosis, macrophage STAT1 deficiency leads to attenuated atherosclerosis, resulting from a decrease in macrophage lipid accumulation, macrophage apoptosis, and plaque necrosis." (PMID 22407286, 2012). "This is in line with the KEGG-analysis of our IFNγ-responsive STAT1-dependent integrative genes, which predominantly linked these genes to lipid metabolism and atherosclerosis-related pathways, whereas STARNET analysis identified high association with LDL cholesterol and diseased vessel traits." (PMID 40607379, 2025). "Hence future studies should seek to investigate the impact of ERK1 deficiency and STAT1 serine 727 phosphorylation on key atherosclerosis‐associated processes in endothelial cells, smooth muscle cells, and other immune cells." (PMID 34569651, 2021). "However, the STAT1 S727A modification had the most pronounced effect on plaque inflammation and atherosclerosis‐associated parameters." (PMID 34569651, 2021).
atherosclerosis (continued). "In addition, the expression of more genes implicated in various atherosclerosis‐associated cellular processes was inhibited in BMDM from STAT1 S727A mice compared to ERK1−/− mice." (PMID 34569651, 2021). "As such, a predefined STAT1-target gene signature could be developed as a novel diagnostic tool to monitor and diagnose plaque phenotype in human atherosclerosis." (PMID 25478796, 2014). "Based on our recent and current findings and in analogy to biomarker assays connected to cancer and transplant rejection, a predefined STAT1-target gene signature could be developed as a novel diagnostic tool to monitor and diagnose plaque phenotype in human atherosclerosis." (PMID 40607379, 2025). "To further substantiate the overlap between human atherosclerosis and mouse atherosclerosis models and the potential involvement of MØ-dependent STAT1-integrative genes we additionally included a bulk RNA-seq data set from HFD fed ApoE knockout mice aorta." (PMID 40607379, 2025). "Using data mining of human plaque transcriptomes, we previously unraveled increased expression of STAT1-dependent proatherogenic genes in human atherosclerosis." (PMID 40607379, 2025). "Fourth, we acknowledge the need for systematic protein-level and experimental validation of our preselected 24 STAT1-integrative gene set to confirm their precise functions in atherosclerosis." (PMID 40607379, 2025). "This highlights the overlap between human atherosclerosis and mouse atherosclerosis models and the potential involvement of STAT1-integrative genes in a MØ-dependent manner." (PMID 40607379, 2025). "Our findings revealed that m6A modification plays a pivotal role in the upregulation of Kdm6b in response to IFN-γ stimulation, which is essential for the phosphorylation of Stat1-induced macrophage activation-mediated atherosclerosis development." (PMID 41423554, 2025). "Fifth, the study primarily focuses on the role of STAT1 in MØ, potentially underestimating the contributions of other transcription factors, cell types and signaling pathways involved in atherosclerosis." (PMID 40607379, 2025). "This study investigated the role of MØ STAT1-mediated signaling in atherosclerosis progression through multi-omics integration of IFNγ-induced MØ and expression analysis in human and mouse atherosclerotic lesions." (PMID 40607379, 2025). "In the present study, we revealed that LSS-mediated IKKε phosphorylation promoted the expression of NLRP3 via activating the downstream transcription factor STAT1, leading to endothelial cell pyroptosis and atherosclerosis." (PMID 38315275, 2024). "Emerging works of research have identified a key role of STAT1 in the development and progression of cardiovascular disease, particularly atherosclerosis." (PMID 38315275, 2024). "Our group’s study showed that in macrophages, IFN-γ downregulates the expression of ABCA1 by activating the JAK/STAT1 signaling pathway, thereby promoting the development of atherosclerosis." (PMID 37670950, 2023). "We focused on Stat1 (Signal Transducer and Activator of Transcription-1) due to its involvement in Pdgfrβ signaling in several disease states such as atherosclerosis and Kosaki overgrowth syndrome." (PMID 37002214, 2023). "With regard to the regulatory effect of LDLs on JAK/STAT signaling in human diseases, a microarray analysis indicated that ox-LDLs in atherosclerosis strongly affect the JAK-STAT signaling pathway by acting through STAT1 and STAT2." (PMID 37900720, 2023). "One study recently reported that miR-139-5p inhibited apoptosis of human arterial smooth muscle cells in the process of atherosclerosis via downregulating Stat1." (PMID 36927608, 2023).